APOB (apolipoprotein B)
Diseases named in the same sentence as APOB in open-access papers (continued):
Sharing a sentence is not in itself a finding about the gene and the disease.
lung carcinoma (22 papers, 2006 to 2025). "The observed mediation effects highlight the considerable influence of neutral ceramidase on the lung cancer risk reduction achieved by APOB and APOC3 inhibition." (PMID 38034491, 2023). "Neutral ceramidase mediated 8.1% and 9.5% of the reduced lung cancer risk in ever-smokers via ApoB and TG reduction by APOB inhibition, respectively, and mediated 8.7% of the reduced LUAD risk via ApoB reduction by APOC3 inhibition." (PMID 38034491, 2023). "The observed causal relationships between APOB inhibition and reduced lung cancer risk in ever-smokers and LUAD risk are particularly noteworthy, as neutral ceramidase plays a significant mediating role in these relationships." (PMID 38034491, 2023). "The observed mediation effects highlight the considerable influence of neutral ceramidase on lung cancer risk reduction achieved by APOB and APOC3 inhibition." (PMID 38034491, 2023). "In this drug-target MR analysis, we assessed the effects of LLDs on lung cancer risk via six LLD targets (APOB, APOC3, HMGCR, LPL, NPC1L1, and PCSK9), comprising 12 lipid-lowering pathways." (PMID 38034491, 2023). "Additionally, APOB inhibition decreased the risk of lung cancer in ever-smokers via LDL (OR 0.82, 95% CI 0.71–0.96, p = 0.040) and TG (OR 0.62, 95% CI 0.46–0.83, p = 0.015) reduction by 1 SD." (PMID 38034491, 2023). "Studies have shown a loss of APOA1 and APOB expression in lung cancer patients." (PMID 38067270, 2023). "Our findings revealed that APOB inhibition decreased the lung cancer risk in ever-smokers and SCLC." (PMID 38034491, 2023). "Interestingly, increasing studies uncover that loss‐of‐function mutations of APOB frequently occur in multiple cancers including melanoma, liver cancer, stomach, esophageal, head and neck, uterine, and lung cancers." (PMID 34997982, 2022). "Furthermore, a study involving 1151 individuals demonstrated that high levels of ApoB may increase the risk for lung cancer and colorectal cancer." (PMID 39193372, 2024). "Previous studies have reported significantly abnormal APOB expression in plasma exosomes of lung cancer patients with liver metastasis, suggesting its potential as a novel biomarker for diagnosing lung cancer." (PMID 41011152, 2025). "Although the exact pathways are not the same across different types of cancer, targeted therapies for lung cancer have been found to induce expression of cytosine deaminases like APOBECs (apolipoprotein B mRNA editing enzymes, catalytic polypeptide-like)." (PMID 39336976, 2024). "In this study, the impact of the apolipoprotein B mRNA-editing catalytic subunit-like (APOBEC) enzyme APOBEC3B (A3B) on epidermal growth factor receptor (EGFR)-driven lung cancer was assessed." (PMID 38049664, 2024). "The increased APOB/APOA1 ratio correlates with a higher incidence of lung cancer in both males and females." (PMID 38067270, 2023). "Associations of APOB, APOC3, and HMGCR inhibition and the LPL agonist with distinct lung cancer risks underscore the multifaceted nature of these relationships." (PMID 38034491, 2023). "Associations of APOB, APOC3, and HMGCR inhibition and LPL agonist with distinct lung cancer risks underscore the multifaceted nature of these relationships." (PMID 38034491, 2023). "APOB inhibition significantly decreased the risk of lung cancer in ever-smokers [odds ratio (OR) 0.81, 95% confidence interval (CI) 0.70–0.92, p = 0.01] and SCLC (OR 0.70, 95% CI 0.55–0.88, p = 0.014) via ApoB reduction by 1 standard deviation (SD)." (PMID 38034491, 2023). "In this study, we performed a comprehensive screening of radiosensitization targets in human lung cancer cell line A549 using an shRNA library and identified apolipoprotein B mRNA editing enzyme catalytic subunit 3G (APOBEC3G: A3G) as a candidate target." (PMID 35563460, 2022). "This suggests that neutral ceramidase may play a critical role in the development of smoking-induced lung cancer, with APOB inhibition potentially acting as a protective factor." (PMID 38034491, 2023).
lung carcinoma (continued). "A previous study found that a decrease in ApoB in lung cancer leads to an increase in oxidative stress, and an increase in ApoB may presumably be related to a reduction in oxidative stress." (PMID 38260151, 2023). "APOBEC (Apolipoprotein B mRNA editing enzyme, catalytic polypeptide-like) enzymes may involve in mutagenic processes in multiple cancer types, including lung cancer." (PMID 26459911, 2015). "In addition, our study is the first to report that APOB is correlated with lung cancer prognosis." (PMID 29728103, 2018). "It was also found that the rate of oxidative stress is elevated in patients with a higher APOB/APOA1 ratio, adding to the speculation that these apolipoproteins can increase the incidence of lung cancer." (PMID 38067270, 2023).
liver cancer (21 papers, 2014 to 2025). An epithelial or non-epithelial malignant neoplasm that arises from the liver. "Conversely, the study reveals a cause-effect relationship between TC, TG, LDL, APOA-I, and APOB with a decreased risk of liver cancer." (PMID 38605235, 2024). "As the apolipoprotein of LDL, the decrease of APOB level has also been identified as a causal risk factor for liver cancer." (PMID 38605235, 2024). "Lastly, in addition to cystatin C, apolipoprotein B, phosphate, monocyte count, males and those of smoking history were associated with liver cancer." (PMID 38263244, 2024). "On the contrary, genetically determined higher TC, TG, LDL, APOA-I, APOB level is associated with a lower risk of liver cancer." (PMID 38605235, 2024). "APOB has been confirmed to be associated with the pathogenesis of a variety of gastrointestinal malignancies, including liver cancer, gallbladder cancer, esophageal cancer and pancreatic duct adenocarcinoma." (PMID 36171259, 2022). "Specifically, a novel nonsense mutation in exon 26 of APOB (p.K2240X) was responsible for low cholesterol and fatty liver in a large kindred, which might also be responsible for cirrhosis and liver cancer in this family." (PMID 24988079, 2014). "On the contrary, apolipoproteins B (APOB, OR 0.67, 95% CI 0.47–0.97), and low-density lipoprotein (LDL, OR 0.62, 95% CI 0.42–0.92) were negatively related to liver cancer risk." (PMID 38605235, 2024). "Following the adjustment, the inverse association between APOB and LDL levels and the risk of liver cancer became stronger, while waist circumference was found to be unrelated to liver cancer risk." (PMID 38605235, 2024). "As demonstrated in this study, apolipoprotein A1, apolipoprotein B and HDL cholesterol were associated with oesophageal, gastric and liver cancers." (PMID 38263244, 2024). "The number of SNPs (nSNP) in the causal relationship between serum lipid indicators and liver cancer are as follows: 22 for LDL-c, 182 for ApoB, 9 for TG, 83 for TC, 92 for HDL-c, and 267 for ApoA1." (PMID 37746259, 2023). "The strong lipophilic nature of vitamin E has been exploited to design α-tocopherol-bound modified siRNAs (Toc-siRNAs), harnessing its physiological pathways, such as incorporation into lipoprotein, for the targeted delivery to apolipoprotein B (apoB) in liver cancer." (PMID 40943628, 2025). "Research reports on liver cancer and GC have indicated that pre-treatment levels of ApoB in liver cancer patients are significantly lower compared to those in control groups, suggesting that it may serve as a potential predictor for liver cancer." (PMID 39193372, 2024). "A possible causal association is observed between APOB and LDL with decreased risk of liver cancer." (PMID 38605235, 2024). "In addition, the loss of HNF4A reduced ApoB and HNF1A expression and promoted tumor growth, especially in liver cancer." (PMID 36213507, 2022). "Additionally, the knockdown of HNF4α led to substantial reductions in HNF1α and APOB, and RNA-seq data from liver cancer patients also showed that the expression of HNF4α, HNF1α, and APOB mRNA are significantly correlated." (PMID 34771521, 2021). "Therefore, we propose that HNF4A mutations G79C, F83C, and M125I are functional mutations found in liver cancers and that loss of HNF4A function, through its mutation, leads to a reduction in HNF1A and ApoB gene expression with a concomitant increased risk of liver tumorigenesis." (PMID 29899848, 2018). "Therefore, we could not analyze the association between liver cancer and the levels and activity of NPC1L1and APOB." (PMID 37746259, 2023). "RNA-Seq analysis observed a strong correlation between HNF4A expression and expression of its target genes, ApoB and HNF1A, in liver cancers." (PMID 29899848, 2018).
liver cancer (continued). "However, the functional role of APOB in sporadic liver cancer is unknown." (PMID 24988079, 2014). "Liver cancer showed negative correlation with the levels of APOB (OR = 0.502, 95% CI = 0.293 - 0.858)and TC (OR = 0.503, 95% CI = 0.258 - 0.982)." (PMID 37746259, 2023).
Alzheimer disease (20 papers, 2011 to 2026). A progressive, neurodegenerative disease characterized by loss of function and death of nerve cells in several areas of the brain leading to loss of cognitive function such as memory and language. "A Mendelian randomization study suggests that apolipoprotein B potentially contributes to shortened healthspan and increased risk for Alzheimer’s disease." (PMID 38402277, 2024). "In addition, we provide preliminary evidence that APOB increases risk for Alzheimer’s disease, a condition that ends healthspan." (PMID 38402277, 2024). "Interestingly, the Alzheimer disease (AD) subjects carrying ApoE ɛ4 allele had lower ApoA1 levels but higher ApoB levels and there were differences in biomarker levels (e.g., cholesterol, LDL, and ApoB) for each ApoE genotype with reference to ε3ε3 in a UK Biobank study." (PMID 34930329, 2021). "Other studies have shown that brain ApoB bound to αβ plaques in transgenic Alzheimer’s disease mice." (PMID 38295984, 2024). "Excluding variants from in and around the APOE locus led to a marked attenuation of the relationship between genetic instruments for apoB and LDL cholesterol and risk of Alzheimer’s disease in mothers." (PMID 34729547, 2021). "For example, apolipoprotein B (ApoB) is an effective BBB shuttle peptide, and the administration of ApoB-fused NPY successfully increased NPY activities in the brain of an Alzheimer’s disease mouse model, which reversed neurodegenerative pathology." (PMID 35203552, 2022).
colorectal cancer (20 papers, 2017 to 2025). A primary or metastatic malignant neoplasm that affects the colon or rectum. "APOB, a key component of fat metabolism, has previously been reported that apolipoprotein levels are associated with overall cancer risk as well as breast, lung and colorectal cancer risk in men." (PMID 35113866, 2022). "In this context, the Malmö Diet and Cancer Study (n = 17,035 women and 11,063 men) showed that apoB was positively associated with overall cancer risk (HR: 1.06; 95% CI: 1.01–1.10) only in men, as well as with colorectal cancer risk (HR: 1.08; 95% CI: 1.01–1.16) in both genders." (PMID 31936330, 2020). "The ratio of serum apolipoprotein B (apoB) to apolipoprotein A-I (apoAI) had been reported as a prognostic factor in colorectal cancer." (PMID 34979995, 2022). "Recently, the prognostic implications of serum apoAI and apoB in colorectal cancer have been gradually revealed." (PMID 34979995, 2022). "Additionally, the apolipoprotein B and urea were found to have no causal effect on colorectal cancer outcomes in European and Central/South Asian populations, while they did show a causal effect in African populations." (PMID 39440482, 2024). "In this study, we analyzed the correlation between serum APOA1 and APOB levels, and APOB/APOA1 ratio, and their associations with clinicopathologic parameters, the levels of twenty systemic inflammatory markers, and survival in 144 colorectal cancer (CRC) patients." (PMID 28710487, 2017). "APOB is downregulated in CRC (colorectal carcinoma), and its silencing in HCC (hepatocellular carcinoma) resulted in increased cell proliferation rates, indicating an anti-growth property of APOB." (PMID 37628784, 2023).
heart failure (20 papers, 2016 to 2026). Inability of the heart to pump blood at an adequate rate to meet tissue metabolic requirements. "The two-step MR analysis indicated heart failure as a mediating factor in the causal relationship between serum ApoB and TB-BMD, with a mediation proportion of 18.69%." (PMID 40475729, 2025). "Our study also confirmed the mediating role of heart failure and quantified itsproportion in the causal relationship between ApoB and TB-BMD." (PMID 40475729, 2025). "The results of this study support that lowering serum ApoB levels could enhance BMD while preventing the occurrence of heart failure might reduce the harm caused by the decrease in BMD due to elevated ApoB levels." (PMID 40475729, 2025). "The ApoB/ApoA1 ratio had a significant causal relationship with the incidence rate of heart failure in IVW and MR-PRESSO analysis (IVW, OR = 1.090, 95%CI = 1.012,1.174, PFDR=0.038; MR-PRESSO, PFDR=0.045), however, P-values were greater than 0.05 in MR Egger and Weighted median results." (PMID 38310324, 2024). "Furthermore, a recent MR analysisproposed that therapies aimed at lowering lipids related to ApoB might providegreater advantages in lowering the risk of heart failure." (PMID 40475729, 2025). "Heart failure etiology and statin treatment explained 23-24% of the variability in cholesterol, free cholesterol, and ApoB (p <0.001)." (PMID 41736908, 2026). "Heart failure explained 18.69%(2.18%, 35.21%) of the total effect of serum ApoB levels on TB-BMD (p< 0.05)." (PMID 40475729, 2025). "Based on the followingscreening process, we ultimately confirmed that heart failure can mediate thecausal relationship between ApoB and TB-BMD." (PMID 40475729, 2025). "We applied atwo-step MR analysis to assess the mediating effect of heart failure on thecausal relationship between ApoB and TB-BMD." (PMID 40475729, 2025). "The ratio of the serum levels of ApoB: ApoA1 is associated with the severity of CVD, including the risk of aortic stenosis, and is predictive for mortality in patients with heart failure." (PMID 38479648, 2024). "A study in Sweden showed a positive link between ApoB/ApoA-1levels and the onset of heart failure." (PMID 40475729, 2025). "Incorporating lipid quality metrics, such as apoB and HDL functionality, into risk stratification models may enhance clinical decision-making in heart failure populations." (PMID 40725639, 2025). "Studies have found that the plasma apoB/A1 ratio, but not apoB level, is associated with CKD progression and immunoglobulin A nephropathy, although neither apoA1 nor apoB alone is associated with renal dysfunction in heart failure." (PMID 35629966, 2022).
Hyperglycemia (20 papers, 2011 to 2025). An increased concentration of glucose in the blood. "It has been reported that 13 cRA induces blood chemistry abnormalities in humans, such as elevated levels of TGs, TC, apolipoprotein B, calcium and creatine kinase activity, as well as hyperglycaemia." (PMID 32947606, 2020). "Fluid resuscitation with intravenous (IV) glucose is not recommended as short-term infusions of IV glucose may induce hyperglycemia and increase intestinal apolipoprotein B48, a component of chylomicron, and VLDL secretion in humans." (PMID 33291273, 2020). "Previous studies demonstrated that glucosamine could attenuate the vessel injury induced by hyperglycemia, promote apolipoprotein A1 expression and impair hepatic apolipoprotein B100 (apoB100) assembly and secretion." (PMID 26377577, 2015). "Hyperglycemia mediates O-glycation of N-acetylglucosamine (GlcNAc) of various proteins including LDL, membrane phospholipids, and apolipoprotein B." (PMID 26640806, 2016).
arteriosclerosis (18 papers, 2013 to 2026). A vascular disorder characterized by thickening and hardening of the walls of the arteries. "It has been hypothesized that accumulation of lipids in arteries—arteriosclerosis—is intrinsically linked to the accumulation of toxic biliary lipids seen in the development of PSC40 suggesting a potential role for APOB in the development and progression of PSC in UC patients." (PMID 39944929, 2025). "The correlation of homocysteine ​​with hyperlipoproteinemia, apolipoprotein B and elevated blood pressure indicates that homocysteine ​​can be a marker of the progression of arteriosclerosis." (PMID 36685849, 2022). "Higher very-low-density lipoprotein cholesterol (VLDL-C) and apolipoprotein B (Apo-B) levels and lower high-density lipoprotein cholesterol (HDL-C) and Apo-A1 levels are associated with an increased risk for arteriosclerotic cardiovascular disease (ASCVD)." (PMID 32460759, 2020). "With high concentrations of ApoB, glomerular endothelial cells and renal vessels may undergo a high level of oxidation stress and inflammation, and arteriosclerosis occurs in small and medium vessels, leading to decreased eGFR and CKD progression." (PMID 37124758, 2023). "First, the structure of apolipoprotein B-100 in Lp(a) is similar to that of LDL-C, which can enhance endothelial cell adhesion and molecular expression, interfere with vascular permeability, and promote foam cell formation, thus causing arteriosclerosis." (PMID 36002888, 2022). "Moreover, visceral obesity can increase the secretion of very low-density lipoproteins, inhibit apolipoprotein B degradation and contribute to the formation of smaller low-density lipoproteins, which are closely related with the incidence of arteriosclerosis." (PMID 31970098, 2019). "Age, systolic blood pressure (SBP), apolipoprotein B (APOB), Visceral Adiposity Index (VAI), hip circumference (HC), and plasma arteriosclerosis index (AIP) are important predictors of ASCVD in the rural population of Xinjiang." (PMID 37264356, 2023). "However, combination therapy improved the apoB/apoA1 ratio and increased serum adiponectin levels, suggesting that long-term combined administration of vildagliptin and metformin may have an inhibitory effect on arteriosclerosis." (PMID 29017497, 2017).